GSN (gelsolin)
Diseases named in the same sentence as GSN in open-access papers (continued):
Sharing a sentence is not in itself a finding about the gene and the disease.
colorectal cancer (15 papers, 2012 to 2025). A primary or metastatic malignant neoplasm that affects the colon or rectum. "The present study aimed to investigate the elusive expression pattern of CDC42, TAGLN, and GSN genes in patients with high and low-risk polyp samples, and also colorectal cancer patients and their adjacent normal tissues." (PMID 37365287, 2023). "Lastly, the study suggests the potential utility of the CDC42, TAGLN, and GSN genes as diagnostic or prognostic markers for colorectal cancer." (PMID 37365287, 2023). "Indeed, Galectin-3-binding protein (LGALS3BP), gelsolin (Gsn), and Spartin (Spg20), which are associated with a favorable clinical outcome in colorectal carcinoma are downregulated in APLN-expressing cells and upregulated in APLN-DM-expressing cells." (PMID 39962271, 2025). "The low GSN expression in colon cancer tissues is a favorable factor that improves the prognosis of colon cancer patients due to the silencing of GSN impedes colorectal cancer cell migration and invasiveness and induces cell cycle stagnation." (PMID 37035750, 2023). "While our study's findings suggest the potential prognostic value of the CDC42, TAGLN, and GSN genes in colonic polyp lesions and colorectal cancer, it is essential to acknowledge certain limitations." (PMID 37365287, 2023). "Ultimately, this study provides evidence on the molecular mechanism by which GSN and PRDX4 mediate an invasiveness pathway in colorectal cancer cells associated with the pathological stage IV lymph node-positive metastasis of CRC." (PMID 35804959, 2022). "A high expression of gelsolin in colorectal carcinoma was shown to increase the cellular migratory potential." (PMID 34631538, 2021). "GSN was initially reported to be reduced in many cancers, including gastric, breast, and colorectal cancers, and is recognized as a tumour suppressor gene." (PMID 32377190, 2020). "Although this observation is the first for pGSN, it supports the prognostic significance of total GSN expression in pancreatic cancers, gynecological cancers, colorectal cancers, and head-and-neck cancers." (PMID 31700155, 2020). "Using microarray data of human colorectal cancer tissues from Gene Omnibus, we found that gelsolin gene expression positively correlates with urokinase plasminogen activator (uPA), an important matrix-degrading protease invovled in cancer invasion." (PMID 27391159, 2016). "To understand the involvement of gelsolin in uPA-mediated invasion in colorectal cancer in vivo, we analyzed the correlation between gelsolin and uPA gene expression." (PMID 27391159, 2016). "Based on the microarray data of tumor tissues from Gene Omnibus (GEO), gene expression of gelsolin showed a signifcant positive correlation with uPA in colorectal cancer." (PMID 27391159, 2016). "In the current study we also investigated the contribution of a number of MMPs in the gelsolin-mediated invasion in colorectal cancer cells." (PMID 22927998, 2012). "In this study, we show that invading populations of tumor cells enriched in gelsolin are found in both primary as well as metastatic human colorectal cancers." (PMID 22927998, 2012). "Low levels of Gelsolin have been identified as a potential colorectal cancer biomarker in a Chinese population." (PMID 22984625, 2012). "We investigated the levels of secreted uPA protein in the conditioned media of gelsolin-overexpressing colorectal cancer cells obtained after 48 hours of serum-deprivation, using enzyme-linked immunosorbent assays (ELISA)." (PMID 22927998, 2012). "Microarray analysis and quantitative PCR indicate that gelsolin overexpression induces the upregulation of invasion-promoting genes in colorectal cancer cells, including the matrix-degrading urokinase-type plasminogen activator (uPA)." (PMID 22927998, 2012). "Our observations indicate that gelsolin confers invasive capacity in colorectal cancer cells, which are consistent with the reported effects of gelsolin in other types of cells." (PMID 22927998, 2012).
colorectal cancer (continued). "Gelsolin’s influence on the invasive activity of colorectal cancer cells was investigated using overexpression and small interfering RNA knockdown." (PMID 22927998, 2012). "Together with the well-established functions of gelsolin in cytoskeletal dynamics, our findings implicate gelsolin as a regulatory determinant of the uPA cascade, with significant impact on colorectal cancer invasion." (PMID 22927998, 2012). "HCT116 was observed to express intermediate levels of gelsolin in a panel of colorectal carcinoma cell lines investigated." (PMID 22927998, 2012). "Taken together our data indicated that in addition to its pro-migratory role, gelsolin promotes invasion in the colorectal carcinoma cells predominantly via increased expression and secretion of uPA." (PMID 22927998, 2012). "Moreover, ATG101 is essential for tissue homeostasis in both adult brains and midguts and mediates GSN and OAS2, which are positively and negatively associated with the recurrence of colorectal cancer, respectively." (PMID 35592424, 2022). "Moreover, our clinical data from colorectal cancer patient gene expression profiles reveals a positive corelation between gelsolin expression and uPA expression, suggesting a clinical significance of gelsolin in promoting cancer invasion." (PMID 27391159, 2016). "Our data suggests that gelsolin is further upregulated along the metastatic tumor borders and may promote secondary spread of colorectal cancer cells within the primary and secondary host tissues." (PMID 22927998, 2012). "We show that gelsolin is required for invasion of colorectal cancer cells through matrigel." (PMID 22927998, 2012). "Besides modulating the mRNA levels of uPA, we also found that gelsolin regulates uPA secretion by colorectal cancer cells." (PMID 22927998, 2012). "The increased proteolytic ability of gelsolin-overexpressing cells, as ascertained by our zymographic analysis, corroborates with earlier observations from the transwell invasion assay which showed that gelsolin conferred invasiveness in colorectal cancer cells." (PMID 22927998, 2012). "In the context of colorectal cancer, the genes CDC42, TAGLN, and GSN have gained increasing recognition due to their significant involvement in key processes related to cancer progression and metastasis." (PMID 37365287, 2023). "Taken together, our study provides in-depth mechanism in gelsolin-mediated invasion through modulating intracellular O2.- levels to enhance uPA secretion and invasion, and this pathway may contribute to invasion and dissemination of cancer in colorectal cancer patient." (PMID 27391159, 2016).
COVID-19 (15 papers, 2020 to 2025). A disease caused by infection with severe acute respiratory syndrome coronavirus 2. "Recently, a panel of five proteins with downregulated expression, namely, albumin (ALB), apolipoprotein A1 (APOA1), apolipoprotein C1 (APOC1), gelsolin (GSN), and transferrin (TF), was identified as a core signature associated with the severity of COVID-19." (PMID 34471261, 2021). "Fourth, GSN has been shown to modulate the function of immune cells involved in the pathogenesis of severe COVID-19, such as neutrophils and macrophages." (PMID 39130641, 2024). "Given the critical role of GSN in regulating inflammation and maintaining alveolar-capillary barrier integrity, it has emerged as a promising therapeutic target for severe COVID-19." (PMID 39130641, 2024). "Gelsolin (GSN), an actin-binding protein with anti-inflammatory and immunomodulatory properties, is a promising therapeutic target for severe COVID-19." (PMID 39130641, 2024). "Despite these challenges, the multifaceted biological activities and promising preclinical and clinical evidence of GSN make it an attractive candidate for the treatment of severe COVID-19." (PMID 39130641, 2024). "For this reason, reduced levels of GSN have been observed in the serum and plasma of COVID-19 patients with worse outcomes, constituting a finding that is in agreement with our results." (PMID 37371071, 2023). "Our observation of reduced serum DNase activity confirms a previous study and builds on studies showing reduced plasma concentrations of Gelsolin in COVID-19; Gelsolin depolymerizes filamentous actin, an inhibitor of DNAse activity." (PMID 36139476, 2022). "Plasma gelsolin is particularly effective towards S1-induced IL-8 and TNF-α secretion, both cytokines with a potent ability to impair endothelial permeability that has been widely associated with poor clinical outcomes for patients with COVID-19." (PMID 36434734, 2022). "Gelsolin is a calcium and phosphatidylinositol 4,5-bisphosphate (PIP2)-regulated protein with the ability to cap and sever actin filaments, and low levels of plasma gelsolin, one of the two main isoforms of the protein, are present in patients with severe COVID-19." (PMID 36434734, 2022). "Gelsolin (GSN), a ubiquitous actin-binding protein, is a promising therapeutic candidate for severe COVID-19." (PMID 39130641, 2024).
melanoma (15 papers, 2016 to 2025). A malignant, usually aggressive tumor composed of atypical, neoplastic melanocytes. "The pro-apoptotic N-terminal of GSN causes structural changes and apoptosis in the melanoma A7 cells." (PMID 36291171, 2022). "We have previously demonstrated that GSN resides in the invadopodia of melanoma cells, where it interacts with the Arp3 protein, which, as a component of the Arp2/3 complex, binds actin." (PMID 40597347, 2025). "We found that GSN expression produces three GSN isoforms in human melanoma cell lines: two cytosolic (B and C) and one secretory (A)." (PMID 40597347, 2025). "To investigate the role of these GSN isoforms, we used the melanoma A375 cell line with GSN knockout to restore the production of only one GSN isoform at a time in these cells." (PMID 40597347, 2025). "The results showed that the transcripts for GSN's A, B, and C isoforms are present in various human skin melanoma cell lines and in normal and melanoma tissues." (PMID 40597347, 2025). "All the GSN isoforms studied participate in both individual and collective migration of melanoma cells." (PMID 40597347, 2025). "Our previous studies have shown that GSN affects the 3D movement of melanoma cells, so we decided to investigate the role of GSN isoforms in this process." (PMID 40597347, 2025). "Lastly, we show that in melanoma tissue, the transcript for GSN-B is produced at the highest level among the transcripts coding for the studied GSN isoforms." (PMID 40597347, 2025). "Melanoma cells were found to produce and secrete all the GSN isoforms studied, although only the A isoform of GSN possesses a signal sequence indicating protein secretion." (PMID 40597347, 2025). "In melanoma A7 cells, GSN is cleaved at the linker site by caspase-3 to produce two fragments; a 39-kDa N-terminal GSN (pro-apoptotic) and a 41-kDa C-terminal GSN (anti-apoptotic)." (PMID 36291171, 2022). "ACTBL2 as a binding partner of gelsolin (GSN), has also been attributed to increasing cell proliferation in human colorectal adenocarcinoma and melanoma cells." (PMID 35770079, 2022). "Fujita and colleagues demonstrated that GSN overexpression inhibited migration and acted as a metastasis suppressor in murine B16a melanoma cells." (PMID 34440617, 2021). "We have previously shown that GSN resides in invadopodia of melanoma cells, where it interacts with Arp3, a known invadopodium constituent." (PMID 34440617, 2021). "Altogether, we prove that GSN is an important player in A375 cells motility, and its role in melanoma biology should be further studied, especially in the context of protrusion on ECM proteins." (PMID 34440617, 2021). "Previously, we reported high gelsolin (GSN)—an actin-binding protein—levels in melanoma cell lines and GSN’s importance for migration of A375 cells." (PMID 34440617, 2021). "We show that GSN is important for melanoma cell migration, predominantly on laminin, which is one of the main components of the skin’s BM." (PMID 34440617, 2021). "In another study, we identified in two melanoma cell lines new molecular partners of GSN, both in the cell nucleus and in a cytosolic fraction." (PMID 34440617, 2021). "Even though gelsolin amounts were decreased in human melanoma cells, they expressed GSN at a relatively higher level than other tumor types (our unpublished data)." (PMID 25352156, 2016). "We noted decreased GSN expression and gelsolin amount in several melanoma cell lines in comparison to normal melanocytes (our unpublished data), corroborating the thesis that gelsolin is a tumor suppressor." (PMID 25352156, 2016). "Our previous studies focused on the role of gelsolin in cell motility of human tumor cells with special emphasis on colon adenocarcinoma and melanoma cells." (PMID 25352156, 2016). "Furthermore, we noted the presence of GSN both intracellularly and extracellularly in melanoma tumor samples, indicating that human melanoma cells produce diverse GSN isoforms in vivo." (PMID 40597347, 2025).
melanoma (continued). "We found that in skin melanoma tissue, the highest amount of transcript among the studied GSN isoforms was noted for GSN-B, which could imply that this isoform is more important for melanoma progression than GSN-A and GSN-C." (PMID 40597347, 2025). "Nonetheless, our outcomes, including those from experiments on zebrafish embryos, indicate that a mixture of GSN isoforms seems to be responsible for the proper functioning of melanoma cells, enabling them to maintain both an appropriate proliferation rate and invasive potential." (PMID 40597347, 2025). "Furthermore, GSN’s localization can be both intracellular and extracellular, and we demonstrate that several melanoma cell lines produce all three studied here GSN isoforms, resulting in the presence of both secreted and intracellular GSN." (PMID 40597347, 2025). "Published data showed that GSN played an important role in melanoma cell migration." (PMID 37958747, 2023). "We suspect that the involvement of GSN in the migration of melanoma cells on the laminin-coated surface may be related to the interaction of GSN with the non-integrin laminin receptor (LamR), which we have shown earlier." (PMID 34440617, 2021). "There are only a few papers focusing on GSN’s role in the biology of melanoma." (PMID 34440617, 2021). "In addition, several reports indicated GSN as a protein affecting human colon cancer and melanoma cell motility." (PMID 32664456, 2020). "It is of course possible that other signaling pathways play a role in neural crest cells fate regulation and thus upstream of Sox10 could regulate GSN expression during embryonic development and formation of melanocytes and melanoma in adult organisms." (PMID 25352156, 2016). "Therefore, to support the well-being of melanoma cells, a mixture of GSN isoforms must be produced." (PMID 40597347, 2025). "Indeed, as shown for melanoma, in situ tumor cells exhibited high levels of GSN." (PMID 40597347, 2025). "Thus, we show here for the first time that GSN is crucial for A375 melanoma cells invasion." (PMID 34440617, 2021). "Therefore, because of that and because there is still a large gap in understanding the role of GSN in melanoma cells, we decided to evaluate the influence of GSN on the ability of A375 cells to move on the main fibrous constituents of the BM, i.e., laminin and collagen type IV." (PMID 34440617, 2021). "Comprehensive analyses of human melanoma cells revealed a specific interaction between polymerized ACTBL2 and the multifunctional actin-binding protein gelsolin in the edge of lamellipodia as protrusions conducting cellular migration." (PMID 38114558, 2023). "Functional examinations in human melanoma cells revealed an interaction between ACTBL2 and gelsolin in the course of cellular lamellipodia formation." (PMID 38114558, 2023). "To address this, we screened protein expression of five melanoma metastasis suppressors (BRMS1, gelsolin, GAS1, NME1/NM23-H1, and KAI1) following KDELR3 knockdown." (PMID 31949145, 2020). "Overall, we demonstrate that GSN isoforms are produced as a mixture in melanoma cells and are not redundant in their function." (PMID 40597347, 2025). "Our results suggest the involvement of GSN in the interaction between laminin and melanoma cells since cells lacking GSN expression had a significantly impaired ability to migrate both spontaneously and collectively." (PMID 34440617, 2021). "Finally, the expression levels of CFL, GSN and HYOU1 proteins were evaluated on some representative bioptic samples from melanoma patients." (PMID 30290833, 2018). "To date, no studies have been conducted to determine whether GSN diverse isoforms are produced by melanoma cells in vivo and melanoma cell lines." (PMID 40597347, 2025).
melanoma (continued). "The results we described suggest a significant role of GSN in the interaction between melanoma cells and laminin 1, as cells lacking GSN production showed a markedly reduced potential for spontaneous and collective migration compared to control cells on a laminin 1-coated surface." (PMID 40597347, 2025).
Alzheimer disease (14 papers, 2010 to 2025). A progressive, neurodegenerative disease characterized by loss of function and death of nerve cells in several areas of the brain leading to loss of cognitive function such as memory and language. "Gelsolin is an anti-oxidant and anti-apoptotic protein that has been implicated as a therapeutic target in Alzheimer disease since it has been shown to reduce amyloid load by inhibiting Abeta fibrillization in animal studies." (PMID 21850163, 2011). "On the other hand, in recent studies overexpression of gelsolin restored the impaired mitochondrial activity associated with CNS degeneration in the course of Alzheimer's disease (AD)." (PMID 21040581, 2010). "Interestingly the down regulation or proteolytic cleavage of gelsolin has been linked to the development of Alzheimer’s disease." (PMID 30691166, 2019). "Gelsolin (GSN), which plays a role in many diseases, for example, Alzheimer’s disease, heart failure, or many types of cancer, is one of the most prevalent ABP." (PMID 41148856, 2025). "Primarily, we found several aging (klotho, major vault 1, gelsolin, huntingtin, and fragile X mental retardation protein) and Alzheimer’s disease (ADAM10, apoE receptor, ChAT, APP, and PSEN1; most of these are also involved in aging) related sequences." (PMID 32449011, 2020). "A recent paper reported plasma gelsolin is decreased and correlated with rate of decline in Alzheimer's disease." (PMID 23880145, 2013). "Yet a pioneer study has demonstrated that peripherally expressed plasma gelsolin can affect amyloid-β dynamics in the CNS in two mouse models of Alzheimer's disease (AD)." (PMID 21936896, 2011).